WNT10B (Wnt family member 10B)
Description:
Member of the Wnt ligand gene family that encodes for secreted proteins, which activate the Wnt signaling cascade. Specifically activates canonical Wnt/beta-catenin signaling and thus triggers beta-catenin/LEF/TCF-mediated transcriptional programs. Involved in signaling networks controlling stemness, pluripotency and cell fate decisions. Acts in the immune system, mammary gland, adipose tissue, bone and skin.
Synonyms: WNT-12; SHFM6; STHAG8
Tractability: Antibody: UniProt places it where antibodies can reach, with high confidence; its Gene Ontology location is reachable by antibodies, with high confidence; UniProt predicts a signal peptide or a membrane-spanning region.
Gene: Protein-coding gene on chromosome 12 (48,965,340 to 48,971,735, reverse strand). Ensembl gene ENSG00000169884.
Subcellular location: Secreted, extracellular space, extracellular matrix; Secreted
Subcellular location (Human Protein Atlas): Golgi apparatus; Predicted to be secreted
Pathways (Reactome):
Signal Transduction: Class B/2 (Secretin family receptors); WNT ligand biogenesis and trafficking
Developmental Biology: Transcriptional regulation of white adipocyte differentiation
Gene Ontology:
Molecular function: protein binding; cytokine activity; frizzled binding; receptor ligand activity; signaling receptor binding
Biological process: canonical Wnt signaling pathway; chondrocyte differentiation; hematopoietic stem cell proliferation; negative regulation of fat cell differentiation; positive regulation of apoptotic process; protein stabilization; cell fate commitment; cellular response to retinoic acid; negative regulation of cold-induced thermogenesis; neuron differentiation; animal organ development; Wnt signaling pathway
Cellular component: extracellular region
Genetic constraint (gnomAD): Loss-of-function variants: 26 observed, 32.88 expected, observed/expected ratio (o/e) 0.79, 90% interval 0.58 to 1.1. The upper end of that interval is the gene's LOEUF score, 1.1, which puts it in group 4 of 6, group 1 being the genes least tolerant of losing a copy. Missense variants: 474 observed, 540.77 expected, observed/expected ratio (o/e) 0.88, 90% interval 0.81 to 0.95. Synonymous variants: 204 observed, 223.53 expected, observed/expected ratio (o/e) 0.91, 90% interval 0.81 to 1.02.
Homologues: Orthologues: chimpanzee WNT10B (100% identical), macaque WNT10B (99% identical), pig WNT10B (98% identical), mouse Wnt10b (97% identical), rat Wnt10b (97% identical), rabbit WNT10B (97% identical), guinea pig WNT10B (96% identical), dog WNT10B (94% identical), tropical clawed frog wnt10b (68% identical), zebrafish wnt10b (66% identical), Drosophila melanogaster Wnt10 (44% identical), Drosophila melanogaster Wnt5 (32% identical), and 4 more. Paralogues in human: WNT10A (62% identical), WNT6 (39% identical), WNT4 (37% identical), WNT2B (36% identical), WNT2 (35% identical), WNT1 (35% identical), WNT3A (35% identical), WNT5A (35% identical), WNT7B (35% identical), WNT3 (35% identical), WNT7A (35% identical), WNT5B (34% identical), and 6 more.
Diseases named in the same sentence as WNT10B in open-access papers:
WNT10B is named in the same sentence as 93 diseases in open-access papers, as found by Europe PMC text mining. Sharing a sentence is not in itself a finding about the gene and the disease. The quoted sentences say what the papers report.
breast carcinoma (23 papers, 2006 to 2025). "It has been shown that high expression of Wnt10b is associated with the survival and metastases in breast cancer and prostate cancer." (PMID 34872582, 2021). "Abnormal expression of Wnt10b can lead to diseases such as breast cancer, hypertrophy and osteoporosis." (PMID 41430099, 2025). "The last decade of research in breast cancer has produced solid evidence for the oncogenic effects of WNT10B in human triple-negative breast cancer (TNBC)." (PMID 36814601, 2023). "Our prior review summarized the biology of WNT10B in mammary stem cells and mouse models of breast cancer." (PMID 36814601, 2023). "But also in breast cancer, Wnt10b‐positive Exos were suggested as prognostic markers governing breast cancer cell metastasis." (PMID 33207034, 2021). "Wnt10b/β-catenin signaling facilitates HMGA2 expression and cell proliferation in breast cancer, and miR-148a inhibits the invasion of colorectal cancer by targeting Wnt10b/β-catenin signaling." (PMID 34872582, 2021). "Loss of p85a can activate fibroblasts, express high levels of Wnt10b; p85a-/- fibroblast-derived exosomes deliver Wnt10b to breast cancer cells, promoting EMT and inducing Wnt/B-catenin signaling." (PMID 32957712, 2020). "Previous studies suggest that WNT10B regulates hematopoietic, mammary, and mesenchymal stem cells and seems to play a diverse role in several diseases including breast cancer, obesity and osteoporosis." (PMID 31089877, 2019). "In breast cancer, Wnt10B was found to be upregulated to promote metastasis and interfere with the clinical outcome." (PMID 31528218, 2019). "We also identified in two separate cases, affected by AML and breast cancer respectively, a genomic transposable short form of human WNT10B (ht-WNT10B)." (PMID 27853307, 2016). "In summary, these results illustrate for the first time that WNT10B expression has significant clinical relevance and probability for predicting recurrence-free survival in breast cancer for both basal-like and TNBC tumours." (PMID 23307470, 2013). "Our present study is an extension of our previous work, in which we proposed the co-regulated expression pattern of the WNT gene cluster (WNT-1, WNT-6, WNT-10A and WNT-10B) in human breast carcinoma." (PMID 23372744, 2013). "Elevated expression of Wnt10b results in mammary tumorigenesis in mice, and has been detected in human breast carcinoma cell lines." (PMID 23307470, 2013). "To determine the expression of WNT10B in human primary breast cancer, we analysed commercially available tumour microarrays (TMA) consisting of 125 samples of all different subtypes by IHC (TNBC ∼15% of total: Ohio St." (PMID 23307470, 2013). "MA-11 cells were originally isolated from a malignant bone marrow metastasis of a breast cancer patient and express high levels of both WNT10B and HMGA2." (PMID 23307470, 2013). "In this study, we determined if the global gene expression pattern of Wnt10b-driven mouse mammary tumours carries an ‘intrinsic gene signature’, which can be translated to the known phenotypes associated with human TNBC." (PMID 23307470, 2013). "We provide evidence that Wnt10b-induced mammary tumours are devoid of ERα, PR or HER2, and thus can be classified as TN." (PMID 23307470, 2013). "WNT10B, one member of the Wnt family, was first found in human breast carcinoma, and several studies have been performed to identify the relationship between WNT10B and human diseases." (PMID 22927882, 2012). "In conclusion, WNT10B expression from CAFs in a paracrine manner elicits breast cancer progression." (PMID 36814601, 2023). "WNT10B overexpression in MDA-MB-231 breast cancer stem cells increased tumor size in vivo, and shWNT10B decreased the number of mammospheres and colony-forming units compared to controls, further confirming a role for WNT10B in cancer stem cells." (PMID 36814601, 2023).
breast carcinoma (continued). "Furthermore, this process is uniquely regulated by Wnt10b/β-catenin signaling in mammary tumors in vivo and in mouse mammary epithelial cell lines in vitro." (PMID 29281678, 2017). "The Wnt10b-driven tumour mouse model has been shown to be useful to model human breast cancer, but still lacking is direct evidence that WNT10B can be linked to human primary TNBC patients." (PMID 23307470, 2013). "WNT3A, WNT4, WNT6, WNT8B, WNT9A, and WNT10B all are overexpressed in many breast cancer cell lines." (PMID 16933995, 2006). "To this end we illustrate that WNT10B has a predictive survival outcome in both TNBC and basal-like human breast cancer." (PMID 23307470, 2013). "The Wnts that are likely to be involved in mammary specification and early morphogenesis, such as Wnt3a, Wnt6, and Wnt10b, are also genetically altered in MMTV-induced mammary tumours." (PMID 16933995, 2006). "Additionally, the reported role in breast cancer of fetal mammary developmental genes, such as TBX3, WNT-10b, FGF10, and LEF1, highlights their potential clinical relevance as biomarkers and therapeutic targets." (PMID 40001874, 2025). "The authors identified a positive correlation between WNT10B and NSD1 in breast cancer tissue." (PMID 36814601, 2023). "Additionally, CAFs release Wnt10b in exosomes, activating the Wnt/β‐catenin pathway and promoting EMT, ultimately facilitating metastasis of breast cancer cells." (PMID 37605453, 2023). "In breast cancer cells, there is overexpression of WNT3A, WNT4, WNT6, WNT8B, WNT9A and WNT10B." (PMID 35453754, 2022). "However, research in the past decade has not focused on WNT10B in the normal mammary gland but on its role in breast cancer and other tissues (discussed in following sections)." (PMID 36814601, 2023). "Additionally, WNT10B expression could not predict survival outcome of patients of any other breast cancer subtype tested with the KM-plotter." (PMID 23307470, 2013). "We hypothesized that in breast cancer, β-catenin over-expression during tumorigenesis is driven by components of Wnt family members, such as WNT10B or another Wnt-ligand rather than by mutations of members of the Wnt/β-catenin pathway as is the case for sporadic colon cancer." (PMID 23307470, 2013).
Obesity (18 papers, 2010 to 2023). Accumulation of substantial excess body fat. "WNT10B polymorphisms and mutations correlate with many phenotypes, including bone mineral density, obesity, pig litter size, dog elbow dysplasia, and cow body size." (PMID 36814601, 2023). "Subsequently, a genetic association between WNT10B polymorphisms and obesity in Belgian males was shown for three WNT10B SNPs (rs833841, rs4018511, and rs10875902)." (PMID 36814601, 2023). "WNT10b regulates adipogenesis in adipose tissue by inhibiting adipogenic transcription factors associated with obesity." (PMID 37219669, 2023). "WNT10B plays a role in cancer and has been implicated in the pathogenesis of osteoporosis, obesity, oligodontia, tooth agenesis, SHFM, fibrosis, PTSD, asthma, and rheumatoid arthritis." (PMID 36814601, 2023). "Several WNT10B SNPs have been associated with obesity, and WNT10B has been implicated in regulating insulin sensitivity via skeletal muscle cells, leading to improved insulin sensitivity." (PMID 31089877, 2019). "Recent identification of WNT10B mutations in human pedigrees of severe obesity demonstrate that altered activity at this locus contributes to additional defects in mesenchymal derivatives." (PMID 20499361, 2010). "Thus far, we have discussed polymorphisms in the WNT10B locus associated with obesity, dental anomalies, SFHM, and bone mineral density in humans." (PMID 36814601, 2023). "Thus, crosstalk between HO-1 and Wnt10b could be employed therapeutically to suppress adipogenesis, and therefore constitutes an attractive drug development target to combat obesity-associated metabolic complications." (PMID 23497794, 2013). "Aberrant WNT10B signaling leads to several diseases, such as osteoporosis, obesity, split-hand/foot malformation (SHFM), fibrosis, dental anomalies, and cancer." (PMID 36814601, 2023). "The PPARγ2 and SFRP1 expressions as two positives and WNT10B as a negative regulator gene of adipogenesis were evaluated in the scWAT of the individuals with different classes of obesity." (PMID 37219669, 2023). "In contrast, individuals with Class I obesity with lower levels of PPARγ2 and higher levels of WNT10B would have a lower capacity for tissue expansion in response to lipogenesis and excessive loads of lipids." (PMID 37219669, 2023). "Wnt3a and Wnt10b inhibits adipogenesis and related obesity via activating the canonical Wnt pathway." (PMID 34042263, 2021). "Our study suggests low-energy shockwave treatment as a way to modulate a Wnt10b/β-catenin pathway and PPARγ expression, and provides new insights for the treatment of obesity." (PMID 31936603, 2020). "Beside their bone anabolic activities, IGFBP2 and Wnt10b are also known for their anti-obesity activities." (PMID 24810249, 2014). "WNT10B has been indicated as a potential regulator of adipogenesis in vivo and in vitro models of obesity." (PMID 22927882, 2012). "In conclusion, RAL ameliorated estrogen deficiency-induced obesity, adipogenesis, and adipose tissue hypertrophy as well as inflammation via distinct activation of canonical Wnt10b/β-catenin and non-canonical SFRP5 signaling." (PMID 31470850, 2019). "WNT10B levels are suppressed in obesity, allowing adipocyte hyperplasia." (PMID 29514067, 2018). "Since then, WNT10B has been shown to play important roles in many tissue types in normal development (including bone, adipocytes, teeth, skin, hair, immune system, muscle, placenta, and heart) and diseases [including cancer, obesity, osteoporosis, and split-hand/foot malformation (SHFM)]." (PMID 36814601, 2023). "Significant positive correlations existed between the expression levels of WNT10B, sXBP1, and VEGFA, considering all obesity groups (r = 0.7, p = 0.0001 and r = 0.3, p = 0.01, respectively)." (PMID 37219669, 2023). "Based on these data, increases of canonical Wnt10b, β-catenin and non-canonical Wnt5a by RAL are strongly associated with the suppression of obesity during estrogen-deficiency." (PMID 31470850, 2019).
Obesity (continued). "Interestingly, “beiging” of eWAT correlated with increased expression of Wnt10b and IGFBP2, two endocrine/paracrine factors recognized for their anti-obesity and bone anabolic activity." (PMID 24810249, 2014). "Furthermore, ectopic expression of Wnt10b in transgenic mice impairs the development of the adipose tissue and these mice are resistant to HFD induced obesity." (PMID 22253696, 2012).
osteoporosis (11 papers, 2010 to 2025). A condition of reduced bone mass, with decreased cortical thickness and a decrease in the number and size of the trabeculae of cancellous bone (but normal chemical composition), resulting in increased fracture incidence. "L. reuteri prevents Wnt10b downregulation in type 1 diabetic bone because a lower bone-specific Wnt10b expression is linked to osteoporosis." (PMID 38398870, 2024). "Similarly, it was documented that Lactobacillus reuteri administration ameliorates trabecular bone loss, restoring Wnt10b suppression in the bones of mice with glucocorticoid-induced osteoporosis." (PMID 35203401, 2022). "However, osteopenia and osteoporosis have been associated with psoriasis and WNT10B signaling appears to impact bone formation." (PMID 31089877, 2019). "The scaffold's ability to upregulate Wnt4, Wnt5a, and Wnt10b expression enhances osteogenic differentiation, reversing the Wnt inhibition characteristic of osteoporosis." (PMID 41542097, 2025). "It enhanced bone density by increasing osteoclast activity or restoring Wnt10b suppression in mice with glucocorticoid-induced osteoporosis." (PMID 39416651, 2024). "Lactobacillus reuteri administration prevented type-1 diabetes-induced osteoporosis by inhibiting TNF-mediated suppression of Wnt10b." (PMID 39416651, 2024). "Lactobacillus reuteri administration prevents type-1-diabetes-induced osteoporosis by inhibiting TNFα-mediated suppression of Wnt10b; it also enhances bone density via increased osteoblast activity and decreased bone marrow adiposity." (PMID 35203401, 2022). "The observation that Wnt10b-null animals have decreased bone volume by 2 months of age suggests that Wnt10b-null animals represent a model of osteoporosis." (PMID 20499361, 2010). "Furthermore, overexpression of Wnt10b in osteoblasts protected against glucocorticoid-induced osteoporosis (GIO), the most common cause of secondary osteoporosis." (PMID 36814601, 2023). "In addition, WNT10B could potentially be used to treat osteoporosis." (PMID 36814601, 2023). "In another model of secondary osteoporosis, in which osteoporosis is induced by vitamin A, Lactobacillus plantarum HFY15 or Lactobacillus fermentum ZS40 isolated from yak yogurt restored BV/TV and other trabecular properties in rats and increased Wnt10b levels in the bone." (PMID 36814601, 2023). "In our study, JGSQP activated the expression of p-AKT along with multiple bone formation and adipogenesis-related genes (Wnt10b, Osx, BMP2, PPARγ, Fabp4, and Fndc5), suggesting that it may ameliorate murine OVX-induced osteoporosis with KYD by controlling the bone-fat balance via the AKT pathway." (PMID 32963560, 2020).
gastric cancer (9 papers, 2014 to 2024). A primary or metastatic malignant neoplasm involving the stomach. "This study provides a solid basis for further study on the mechanisms and potential therapeutic targets of WNT10B in gastric cancer." (PMID 36814601, 2023). "WNT10B is overexpressed in gastric cancer compared to paired normal tissue and correlates with a higher rate of lymph node metastasis." (PMID 36814601, 2023). "In gastric cancer, Helicobacter pylori upregulates the expression of Wnt10a and Wnt10b, thereby activating the Wnt/β-catenin pathway." (PMID 37608794, 2023). "Wnt10b activates the Wnt/β-catenin signaling pathway and exerts functions in various malignancies, including gastric cancer, colorectal cancer, cervical cancer." (PMID 35200072, 2022). "stem cell marker Oct4 was positively correlated with the expression level of WNT10B in gastric cancer tissues, and Wnt10B may also be involved in the generation and maintenance of gastric cancer stem cells." (PMID 38952556, 2024). "Ligands such as Wnt2, WNT5A, and WNT10B are involved in the EMT in gastric cancer." (PMID 38952556, 2024). "WNT10B is known to regulate gastric cancer progression by promoting EMT." (PMID 38027033, 2023). "Our results showed that HOXC-AS3 could bind to YBX1, thus transcriptionally regulating a large set of genes that are linked to cell proliferation and cell migration in gastric cancer cells, such as MMP7, WNT10B, and HDAC5, thus promoting GC cell proliferation and migration." (PMID 30286788, 2018).
hepatocellular carcinoma (8 papers, 2012 to 2025). A malignant tumor that arises from hepatocytes. "Delivery of miR-192 via hydrogel-based methods inhibits hepatocellular carcinoma progression by specifically targeting WNT10B, encoding Wnt Family Member 10B protein (WNT10B) which plays a crucial role in the GSK3β/Wnt/β-catenin pathway." (PMID 40087755, 2025). "As reported, NSD1 inhibits H3K27me3 methylation to promote Wnt10b transcription in the development of hepatocellular carcinoma." (PMID 34905470, 2021). "The only report in hepatocellular carcinoma, demonstrated that overexpression of WNT10B in the presence of fibroblast growth factor (FGF) promotes cancer cell growth." (PMID 23110045, 2012). "WNT10B is also regulated by NSD1 in hepatocellular carcinoma (see Section 17.14)." (PMID 36814601, 2023). "NCEH1 and WNT10B, and ATP1A3 have been rarely reported to be associated with AD, but WNT10B has an important role in progression of colorectal cancer and hepatocellular carcinoma." (PMID 36506318, 2022). "WNT10B (Wnt Family Member 10B) overexpression has been a target for hepatocellular cancer therapy." (PMID 34199901, 2021). "In hepatocellular carcinoma (HCC) specimens, WNT10B is significantly upregulated compared to normal liver tissue." (PMID 36814601, 2023).
colorectal cancer (7 papers, 2014 to 2022). A primary or metastatic malignant neoplasm that affects the colon or rectum. "Among colorectal cancer cells, researchers have found that miR-148a suppresses cell invasion and migration by targeting wnt10b and modulating Wnt/β-catenin signalling." (PMID 32913459, 2020). "For example, WNT10B is downregulated in colorectal cancers as a result of promoter hypermethylation and, on the contrary, WNT2 is upregulated due to histone modifications." (PMID 33189141, 2020).